RPL13AP20 (ribosomal protein L13a pseudogene 20)
Synonyms: HANR; RPL13A_9_1211
Gene: Transcribed processed pseudogene on chromosome 12 (12,875,499 to 12,876,107, forward strand). Ensembl gene ENSG00000234498.
Diseases named in the same sentence as RPL13AP20 in open-access papers:
RPL13AP20 is named in the same sentence as 6 diseases in open-access papers, as found by Europe PMC text mining. Sharing a sentence is not in itself a finding about the gene and the disease. The quoted sentences say what the papers report.
COVID-19 (1 paper, 2025). A disease caused by infection with severe acute respiratory syndrome coronavirus 2. "In COVID-19, these included RPL13A, RPL6, RPL13, RPLP2, RPS11, UBA52, and the ribosomal pseudogene RPL13AP20." (PMID 41020849, 2025).
lymph node metastasis (1 paper, 2020). "In addition, patients with lymph node metastasis had significantly higher expressions of PGM5P2, HERC2P4 and RRN3P2 but lower expressions of HLA-H and RPL13AP20 than those without lymph node metastasis." (PMID 33378744, 2020).
tumor (3 papers, 2020 to 2023). "Heatmap indicated that NCF1C, HLA-DRB6, HLA-DPB2, HLA-J, HLA-H, HLA-L and RPL13AP20 displayed high expressions in the low-risk group, and thus were categorized as tumor-suppressor pseudogenes in the current study." (PMID 33378744, 2020).
RPL13AP20 also shares sentences with these, for which no sentence is quoted: hepatocellular carcinoma (4 papers); breast carcinoma (1); cancer (1).